ATR (ATR checkpoint kinase)
Diseases named in the same sentence as ATR in open-access papers (continued):
Sharing a sentence is not in itself a finding about the gene and the disease.
cancer (continued). "We designed a cellular model to study the clinically relevant ATR heterozygous mutation found in MSI + cancers." (PMID 35361811, 2022). "Consistently, ATM is frequently mutated in a variety of cancer types, whereas mutations in ATR promote development of melanoma and oropharyngeal cancer syndrome." (PMID 36186482, 2022). "The study of cell cycle checkpoint signaling through ATR, as well as the related pathways implicated in oncogenesis and cancer progression, has resulted in the discovery and development of effective and selective ATR inhibitors (ATRi)." (PMID 35712480, 2022). "Collectively, these findings show that RAD51 inhibition-mediated IRF1 upregulation, a downstream component of ATR/Chk1 signaling, is a critical mechanism underlying PD-L1 expression regulation in cancer cells." (PMID 35646698, 2022). "Because of these critical functions, cancers infrequently involve loss-of-function mutations in the ATR pathway, and a subset of tumors with particular mutations is more vulnerable to ATR pathway inhibition than normal cells." (PMID 35712480, 2022). "ATR is an attractive target because cancer cells with inactivating mutations in ARID1A, ATM, ERCC1, RNASE H2, and XRCC1 are sensitive to ATRi’s in vitro and in vivo, particularly in combination with DNA-damaging agents that target DNA replication forks." (PMID 36130512, 2022). "This feature provides a rationale for targeting both stress kinases (ATM/ATR) in ARID1A-deficient cancers." (PMID 36123603, 2022). "We find that 233 of the 961 ATM and 147 of the 746 ATR residues mutated in cancer are conserved in the budding yeast ATM/ATR proteins Tel1 and/or Mec1." (PMID 33742106, 2021). "Exploiting this concept, ATR inhibitors (ATRi) are in clinical development for the treatment of cancers including those with mutations in the related kinase ataxia telangiectasia mutated (ATM), or high endogenous replication stress." (PMID 34329458, 2021). "This would make sense from a cancer cell perspective because the loss of kinase activity would impact a range of processes that ATM/ATR proteins govern, including cellular proliferation; accordingly, such a mutation would confer little selective advantage." (PMID 33742106, 2021). "We find that the conserved ATM/ATR residues mutated in different cancer types show distinct distribution patterns along the respective polypeptides." (PMID 33742106, 2021). "Se has also been reported to activate ATM/ATR, but this activation is associated with Se-induced DNA damage in cancer cells." (PMID 33875618, 2021). "Among the conserved, four ATM (G2083, G2765, E2868, and S3027) and three ATR (C607, E2378, and G2530) residues are mutated in cancer." (PMID 33742106, 2021). "Reminiscent of the conserved ATM/ATR residues mutated in cancer, majority (12/15) of the Mec1 residues are buried inside the enzyme complex." (PMID 33742106, 2021). "We find that 42% and 32% of the conserved ATM and ATR residues mutated in cancer are in the kinase domains, representing approximately a threefold and twofold enrichment, respectively." (PMID 33742106, 2021). "Here, we review cancer-associated replication stress (RepStress) and its genomic signature, and propose how to utilize RepStress-targeted therapies in the context of ATR inhibitors and Schlafen 11 (SLFN11)." (PMID 34572827, 2021). "Our findings provide insights into the potential functional impact of numerous ATM/ATR mutations found in cancer." (PMID 33742106, 2021). "The majority of the ATM/ATR residues implicated in cancer are buried inside the respective enzyme complexes." (PMID 33742106, 2021).
cancer (continued). "This study provides insights into the genotype-phenotype relationships in ATM/ATR and their cancer-associated variants." (PMID 33742106, 2021). "We experimentally show that both HMCES disruption and A3A expression increase susceptibility of cancer cells to ionizing radiation (IR), oxidative stress, and ATR inhibition, strategies that are often applied in tumor therapies." (PMID 33788831, 2021). "In humans, germline mutations in ATM and ATR lead to Ataxia-Telangiectasia (A-T) and Seckel syndrome, respectively, characterized by a constellation of symptoms, including neurodegeneration, cancer, diabetes, infertility, and microcephaly." (PMID 33742106, 2021). "In particular, APOBEC3A (A3A) has emerged as a major driver of mutagenesis in cancer cells, and its expression results in DNA damage and susceptibility to treatment with inhibitors of the ATR and CHK1 checkpoint kinases." (PMID 33788831, 2021). "In this respect, it was shown that ATR inhibition potentiates cytotoxic effects of PARP inhibition by forced mitotic entry in cancer cells with deficient HRR." (PMID 33888065, 2021). "Recently, it has been discovered that Pol-θ inhibition sensitizes cells to replication stress caused by agents such as topoisomerases poisons or ATR inhibitors, suggesting novel cancer treatments." (PMID 32932697, 2020). "Despite the limited data on ATR inhibitor efficacy in the clinics, patients with ATM-mutated cancer that receives an ATR inhibitor shows a complete clinical response." (PMID 32883316, 2020). "We have shown AUF1-dependent downregulation of ATR in CAF cells, and poor prognosis of patients bearing tumors expressing low level of ATR in both cancer cells as well as cancer-associated fibroblasts." (PMID 32414408, 2020). "As a monotherapy, ATR inhibitors are effective in cancer cells with mutations in various proteins involved in DSB repair, including ATM." (PMID 32731592, 2020). "For instance, KRAS oncogene mutations are common in various cancers and had been found that ATR or GATA2 transcription factor inhibition is synthetically lethal." (PMID 32883316, 2020). "Univariate Cox regression analysis also showed an increased risk for patients with low ATR levels in both stromal fibroblasts (hazard ratio > 1; P = 0.0001) and cancer cells (hazard ratio > 1; P = 0.0012)." (PMID 32414408, 2020). "In the current study, we provide the first clinical evidence that high ATR in MYC overexpressed tumours is associated with aggressive cancer and poor survival." (PMID 30746633, 2019). "Recently, DNA DSB repair has been implicated in regulating the expression of PD‐L1 in cancer cells, and the effect of ATR inhibition on PD‐L1 expression, and consequently on immune surveillance of tumor cells, has been investigated." (PMID 30714316, 2019). "Accumulating evidence demonstrates that ATR-checkpoint kinase 1 (Chk1) pathway can be considered as potential therapeutic strategies for ATM-deficient cancers." (PMID 30975222, 2019). "Brahma-related gene 1 (BRG-1) associated factor complex (BAF) are chromatin remodelers commonly mutated in cancer, and have a recently described role in the initial activation of the DNA damage response by modulating ATR activation." (PMID 30612957, 2019). "Emerging data from these early-phase studies support the preclinical observations of the synthetic lethality of ATR inhibitors in ATM-deficient cancers." (PMID 31018854, 2019).
cancer (continued). "Experimental data have provided a strong rationale for administering ATR inhibitors (ATRi) since they cause synthetic lethality in cancers characterized by deficiency of certain DDR components." (PMID 29770165, 2018). "We have shown here that the ATR level is reduced in most cancer-associated fibroblasts (CAFs) as compared to their adjacent normal counterparts." (PMID 30410668, 2018). "Cancer cells bearing checkpoint/repair-deficiency or oncogene-induced replication stress paradoxically increase ATR-Chk1 signaling expression to tolerate the stress for proliferation and survival." (PMID 29209046, 2017). "In conclusion, ATR-inhibition induces the selective elimination of certain cancer cell subsets, but the underlying genetic determinants remained insufficiently defined." (PMID 26755646, 2016). "We identified a set of DNA-repair proteins, whose knockdown selectively killed ATR-deficient cancer cells." (PMID 26755646, 2016). "ATR kinase signaling is frequently high in cancer cells and this is thought to be associated with replication stress, making ATR an intriguing target." (PMID 26517239, 2015). "One frame-shift mutation, one point mutation G736* (in two independent carcinomas), and one point mutation D1687H in ATR are likely to reduce ATR activity." (PMID 26438152, 2015). "Nonetheless heterozygous ATR gene mutations have been implicated in some human cancer types that also happen to exhibit microsatellite instability, where ATR appears to constitute a haploinsufficient tumour suppressor." (PMID 24416382, 2014). "First, CHO cells as well human cancer cells deficient in XRCC1 were highly sensitive to ATR inhibitors." (PMID 23451157, 2013). "Evidences suggest that BRCA1 part of the "Role of BRCA1, BRCA2 and ATR in Cancer Susceptibility" pathway significantly enhances the ability of TNF-α or IFN-γ to activate transcription from the promoters of NF-κB target genes." (PMID 21226955, 2011). "Based on its central function in the DNA damage response, ATR is a plausible candidate gene for susceptibility to cancer." (PMID 15987455, 2005). "The performed mutation analysis is to our knowledge the first to investigate the possible association of germline ATR mutations with cancer predisposition." (PMID 15987455, 2005). "While the precise mechanisms by which aberrations in ATM, ATR, and DNA-PK contribute to diverse phenotypic outcomes remain unclear, alterations in these genes are strongly linked with specific cancer subtypes." (PMID 40256842, 2025). "By targeting the weaknesses of ATM-deficient cancer cells, this approach not only boosts the effectiveness of ATR inhibitors but also introduces a promising strategy to overcome chemoresistance, paving the way for more innovative and effective treatments for colorectal cancer." (PMID 40256842, 2025).
cancer (continued). "Indeed, a phase I and a phase II clinical trial have tested the ATR inhibitor ceralasertib (AZD6738) in patients with ARID1A loss in different cancers and show durable anti‐tumor activity." (PMID 40170512, 2025). "Furthermore, ATR has been linked to DNA damage-induced NE rupture through phosphorylation of Lamin-A/C, while loss of ATR in cancer cells impedes the progression of tumors, thus rendering ATR as an attractive drug target." (PMID 40983686, 2025). "Furthermore, as with other anti-cancer agents used in clinical settings, both ATR and CHK1 inhibitors are associated with limiting side effects that can impact treatment feasibility and patient outcomes." (PMID 40869030, 2025). "Therefore, it has been argued that ARID1A‐deficient cancers are sensitive to ATR inhibitors, which, in turn, promote apoptosis." (PMID 40170512, 2025). "In addition to inhibiting DNA repair, ATR inhibitors induce unscheduled firing of replication origins, which can result in cancer cell death through genomic alterations caused by faulty replication and subsequent mitotic catastrophe." (PMID 40896397, 2025). "During breast tumorigenesis, highly expressed TOPBP1 may help cancer cells efficiently cope with the sustained replication stress by compartmentalizing itself and associated factors around ATR." (PMID 41392982, 2025). "Similarly, loss of ATM function (common in many cancers) forces a compensatory reliance on the ATR pathway, creating another potent synthetic lethal context." (PMID 41409249, 2025). "Interestingly, apart from its location in the nucleus, ATR is a HSP90 client in the cytosol and ATR has been implicated in mitochondria-related apoptosis in yeast and cancer models." (PMID 40105243, 2025). "ATR pathway inhibitors disable this protective reaction, ultimately causing cancer cell death." (PMID 39962391, 2025). "Thus, our findings imply that addiction to ATR for fork protection and sustainable fork progression is closely associated with vulnerability to ATRis in cancer cells." (PMID 39875375, 2025). "Additionally, the ATR c.2320dup (p.Ile774fs) variant found in multiple tumor types suggests its critical role in the pathogenesis of various cancers, offering a potential target for future therapies." (PMID 39338229, 2024). "Interestingly, a loss-of-function genetic screening of kinomes revealed that Ataxia telangiectasia and Rad3-related protein (ATR) inhibition synergizes with oxaliplatin to induce cancer cell death." (PMID 39271762, 2024). "Indeed, PRMT9 inhibition or expression of XRN2-R946K in AML cells promoted R-loop formation and ATR signaling, which underlies cGAS activation in cancer cells." (PMID 38413714, 2024). "Moreover, ATR inhibition was shown to be toxic in cancer cells harboring ATM mutations, a feature seen in many tumors, especially in combination with PARP inhibitors." (PMID 38880245, 2024). "If POLA1 is thus inhibited in ATR- or CHK1-deficient cancer cells, global RPA exhaustion and therefore replication catastrophe culminating into apoptosis might be the consequence." (PMID 39128273, 2024). "A subset of cancer cells under replication stress may be susceptible to ATR inhibitors, as well as other DDR inhibitors, such as CHK1 or WEE1 under MYC- or CCNE1-induced replication stress." (PMID 37422534, 2023). "For example, loss of ATM in tumors makes tumors more rely on ATR-mediated intra-S and G2/M checkpoints, and inhibition of ATR could selectively kill cancer cells with ATM deficiency." (PMID 38041093, 2023). "AZD6738 specifically synergizes some PARP inhibitors in particular DNA repair-deficient cell lines, providing rationale for scrutinizing synergistic interactions between PARP and ATR inhibitors in immortalized or cancer cell lines that have defects in another HRR-associated gene." (PMID 36794257, 2023).
cancer (continued). "Therefore, it is plausible that some hPOT1 cancer mutations disrupt the ability to resolve GQ structures at telomeres, leading to activation of the ATR pathway and promoting telomerase recruitment to the telomeres." (PMID 37560909, 2023). "To date, little work has been done to identify patient subsets that may respond more favorably to inhibition of ATR signaling outside of core DNA damage repair mutations found in some cancers." (PMID 38032106, 2023). "Targeting ATR may exploit synthetic lethality in cancer cells with impaired compensatory DDR through ATM loss, whether as monotherapy or combined with DNA-damaging drugs." (PMID 36797243, 2023). "More specifically, CHEK1 germline and somatic mutations have been observed in cancers such as breast, endometrial, colorectal and stomach, and germline mutations within ATR have been linked to an increased risk of developing oropharyngeal cancer and other malignancies." (PMID 36358700, 2022). "To test this hypothesis, we designed an isogenic cellular model in HCT116 (CRC, MSI + cancer cell line), which showed that ATR mutation strongly sensitizes cells to SN-38 and VE-822 (ATR inhibitor), both alone and combined." (PMID 35361811, 2022). "Cancer genome sequencing showed a very low ATR or CHK1 mutation or deletion frequency." (PMID 35875060, 2022). "Using a multivariate regression model, corrected for age and genetic ancestry represented by principal components, we found 12 positive correlations between the HRD score and germline variants in five (i.e., BRCA1, BRCA2, PABL2, ATM, ATR) genes across cancer types." (PMID 34572800, 2021). "Cancer‐associated inflammation and cytotoxic treatments such as chemotherapies and radiotherapies are known to cause replication stress, which increases cell reliance on the ATR‐mediated S and G2/M checkpoints activation as countermeasures." (PMID 34977872, 2021). "We wished to examine whether the ATM and ATR residues mutated in a specific cancer type might localize to a distinct region(s) of the respective enzyme complexes." (PMID 33742106, 2021). "While ATM and DNA-PK expression may be lost in human cancer, ATR expression is generally maintained, although mutations and reduced expression levels are sometimes observed." (PMID 34298632, 2021). "Notably, ATR inhibitors are progressing well in the clinic, and ATR haploinsufficiency, arising due to somatic mutations in one allele, is frequent in certain cancers, presenting therapeutic opportunities for POLH inhibition." (PMID 34900730, 2021). "However, several reports indicate that loss of ATR function renders cancer cells sensitive to oncogene-induced replication stress, e.g. in oncogenic RAS-driven tumours." (PMID 34819497, 2021). "However, genetic and pharmacological inhibition of RAD51 further sensitized BL0479-72 cells to TMZ + VE821 compared to control cells, in line with the notion that HR deficiencies increase reliance on ATR activity in cancer cells." (PMID 34676045, 2021). "While, ATR loss of function is rare in cancers, ATR inhibition may be particularly potent in cancer cells with other, specific mutations, such as in ATM, when compared to normal cells." (PMID 33498525, 2021). "Consequently, ATR inhibitors (ATRi) are in clinical development for the treatment of cancers, including tumours harbouring mutations in the related kinase ATM." (PMID 34329458, 2021).